TLR4 (toll like receptor 4)
Diseases named in the same sentence as TLR4 in open-access papers (continued):
Sharing a sentence is not in itself a finding about the gene and the disease.
breast cancer (continued). "It appears that elevation of TLR4 expression by TOPK in LPS response might occur via NF-kB or MMP9-mediated positive feedback loop leading to breast cancer invasion and metastasis, suggesting a possible mechanism regarding TOPK-mediated regulation of TLR4." (PMID 28212583, 2017). "Here we also found that Chinese propolis and CAPE activated caspase 3- the executor of apoptosis in LPS-stimulated breast cancer cells, which might be induced by activating autophagy and depressing TLR4 signaling pathway." (PMID 28950845, 2017). "TOPK-mediated regulation of NF-κB activity and MMP9 expression in LPS/TLR4 signaling might be a mechanistic link connecting inflammation to breast cancer malignancy." (PMID 28212583, 2017). "We also hypothesized that LPS-mediated TOPK expression or activity leads to secretion of MMP9 thereby degrading ECM, which then activated TLR4 and enhanced breast cancer cells invasiveness." (PMID 28212583, 2017). "However, recent evidence shows that TLR4 is expressed in a wide variety of tumors such as liver cancer, lung cancer, breast cancer, gastrointestinal cancer, pancreatic cancer." (PMID 28950845, 2017). "To understand the effects and mechanisms of ethanol-extracted Chinese propolis (EECP) and its major constituent - CAPE in inflammation-stimulated tumor, we investigated their effects on Toll-like receptor 4 (TLR4) signaling pathway which plays a crucial role in breast cancer MDA-MB-231 cell line." (PMID 28950845, 2017). "The augmentation of expression of TOPK as well as TLR4 in response to LPS in breast cancer cells suggests that TOPK might mediate LPS-TLR4 signaling leading to breast cancer cell migration." (PMID 28212583, 2017). "Collectively, we conclude that TOPK functions as a key mediator of LPS/TLR4-induced breast cancer cell migration and invasion through regulation of MMP9 expression or activity, implying a potential role of TOPK as a therapeutic target linking LPS-induced inflammation to breast cancer development." (PMID 28212583, 2017). "Thus, the goal of this study was to explore the effects of ethanol extract of Chinese propolis (EECP) and CAPE on lipopolysaccharide (LPS)-stimulated breast cancer MDA-MB-231 cells by testing TLR4 signaling pathway." (PMID 28950845, 2017). "Here we found that Chinese propolis and its major active constituent – CAPE promoted autophagy and inhibited TLR4 signaling pathway to prevent LPS-stimulated breast cancer MDA-MB-231 cells proliferation although the crosstalk between autophagy and inflammation was not known." (PMID 28950845, 2017). "TLR4 and TLR9 signaling have been associated with breast cancer progression due to findings revealing that both LPS and CpG-ODN could promote breast cancer cell migration, invasion and metastatic spreading." (PMID 27187369, 2016). "On the contrary, other studies pointed out that e.g., silencing of TLR4 increased tumor progression and lung metastases in a murine model of breast cancer and that TLR9 agonists could induce apoptosis in A20 lymphoma cells and neuroblastoma cells." (PMID 27187369, 2016). "Moreover, TLR4 expression in breast cancer and ovarian cancer has been correlated to paclitaxel chemoresistance." (PMID 27187369, 2016). "A recent study highlighted that activation of TLR4 by paclitaxel enhances tumor growth and metastasis in breast cancer, and that blocking paclitaxel-induced TLR4 activation in cancer may observably improve therapeutic outcome." (PMID 27323819, 2016). "In vivo studies have suggested that TLR4 agonists can inhibit mammary tumor metastasis." (PMID 26106384, 2015). "Finally, TLR4 protein expression correlated with a decreased survival in a cohort of 144 primary breast cancer patients." (PMID 26392082, 2015). "While loss-of-function mutations affecting TLR4 or P2RX7 have a negative impact on the survival of breast cancer patients, local expression of MX1 constitutes a positive prognostic marker." (PMID 26369701, 2015).
breast cancer (continued). "Instead, we could show that the DAMP, S100A9, also induced pro-inflammatory proteins in breast cancer cells expressing TLR4." (PMID 26392082, 2015). "TLR4 has previously been shown to be expressed in breast cancer." (PMID 26392082, 2015). "Other parameters that might be affected by TLR4 expression in breast cancer cells were also investigated; invasion, apoptosis and proliferation." (PMID 26392082, 2015). "The current study demonstrated that TLR4 expressed on human breast cancer cells may contribute to tumor progression, especially in metastasis." (PMID 25299052, 2014). "Thus, we assessed the expression of MyD88 and TLR4 in 205 breast cancer patients and confirmed that MyD88 and TLR4 expression was correlated with poor DFS and OS." (PMID 25360699, 2014). "Therefore, TLR4-MyD88 signaling pathway activation in tumor biology provides a novel potential target for breast cancer therapy." (PMID 25360699, 2014). "Few studies have investigated MyD88, an important adaptor protein of TLR4, in breast cancer." (PMID 25360699, 2014). "Our previous studies have found that TLR4 expressed higher levels than any other TLRs and knockdown of TLR4 could actively inhibit proliferation and survival of human breast cancer cells MDA-MB-231." (PMID 25299052, 2014). "LPS triggered increased expression of TLR4 downstream signaling pathway protein myeloid differentiation factor 88(MyD88) and resulted in interleukin (IL)-6 and IL-10 higher production by human breast cancer cells." (PMID 25299052, 2014). "Moreover, our study indicated that, after TLR4 stimulation, breast cancer cells produced higher amounts of MMP-2, MMP-9 and VEGF, and as stimulus concentration increased within a certain range, the production of MMP-2, MMP-9 and VEGF also increased." (PMID 25299052, 2014). "Our previous study identified that MDA-MB-231 cells expressed multiple TLRs, especially TLR4, and demonstrated that knockdown of TLR4 could actively inhibit proliferation and survival of breast cancer cells." (PMID 25299052, 2014). "It is unknown which pathway plays the most important role in breast cancer, and little is known about the expression of MyD88 in breast cancer and its correlation with TLR4 in tumor prognosis." (PMID 25360699, 2014). "Herein, we explored a more direct relationship between TLR4 and human breast cancer." (PMID 25299052, 2014). "We concluded that TLR4/MyD88 signaling contributed to their invasive activity of human breast cancer cells via autocrine and/or paracrine which played an active role in human breast cancer metastasis." (PMID 25299052, 2014). "In conclusion, our data confirmed that human breast cancer cell lines and tissue expressed TLR4." (PMID 25299052, 2014). "TLR4 also has the potential to become a disease progression marker in patients with colon cancer or premalignant lesions as well as a biomarker of the aggressive tumor phenotype in laryngeal carcinoma and breast cancer." (PMID 22110526, 2011). "In summary, induction of MTDH by LPS could increase the migration and invasiveness in the TLR4 positive breast cancer cells." (PMID 22195048, 2011). "First, we examined which breast cancer cell lines were TLR4 positive." (PMID 22195048, 2011). "In our study, TLR4 expressed in breast cancer cell line MDA-MB-231, MCF-7 and MDA-MB-468." (PMID 22195048, 2011). "TLR4 played a positive role in the progression of breast cancer cells." (PMID 20618976, 2010). "Taken together, our results suggest RNAi-directed targeting of TLR4 may be a beneficial strategy for breast cancer therapy." (PMID 20618976, 2010). "We sought to characterize the expression of TLR1-TLR10 in the established human breast cancer cell line MDA-MB-231, and to investigate the biological roles of TLR4 in breast cancer cells growth, survival, and its potential as a target for breast cancer therapy." (PMID 20618976, 2010). "Moreover, regardless of HMGB1, TLR4 is associated with a poor prognosis and chemotherapy resistance in breast cancer." (PMID 40727252, 2025).
breast cancer (continued). "Likewise, HMGB1/TLR4/NF-κB signaling mediates metastasis and enhances inflammatory cytokine production in breast cancer, while drug-resistant myeloma cells exhibit increased HMGB1 release, whereby silencing HMGB1 diminishes NF-κB phosphorylation and restores drug sensitivity." (PMID 41465435, 2025). "Engagement of pattern recognition receptors such as TLR2 (for LTA) and TLR4 (for LPS) may play a central role, consistent with studies in cardiomyocytes, intestinal epithelial cells, and breast cancer lines showing that TLR activation modulates DOX uptake and toxicity." (PMID 41156777, 2025). "Notably, the expression of TLR4 in the ductal epithelial cells of the breast tumor microenvironment correlates with the invasiveness of the tumor, indicating its potential role in driving breast cancer progression." (PMID 38903515, 2024). "The results showed that hyperoside may increase the sensitivity of cancer cells to paclitaxel by blocking pro-inflammatory and pro-survival strategies mediated by TLR4 activation mediated by TLR4, validating the beneficial combination to achieve a suitable chemosensitivity in breast cancer." (PMID 37743502, 2023). "Moreover, they demonstrated that the knockdown of TLR-4 could actively inhibit the proliferation and survival of breast cancer cells." (PMID 37735586, 2023). "Additionally, the genetic knockdown of TLR4 inhibited the proliferation of the breast cancer cells." (PMID 37371732, 2023). "Also, APRIL is released by neutrophils through the TLR4-PKR pathway activated by breast cancer." (PMID 37958571, 2023). "Toll-like receptor 4 (TLR4) and phosphorylated signal transducer and activator of transcription protein 3 (pSTAT3) play a prominent role in cancer inflammation and anti-tumor immune response, and their therapeutic targeting is considered a promising strategy for the management of breast cancer (BC)." (PMID 35205801, 2022). "Tumorigenesis and breast cancer progression induced by HMGB1 as a ligand may be mediated via the TLR4/myeloid differentiation factor 88 and RAGE signaling pathways for tumor invasion and metastasis, CSC renewal, epithelial–mesenchymal transition (EMT), drug resistance, and cancer recurrence." (PMID 34638242, 2021). "Furthermore, we reported that Chinese propolis and its major constituent—caffeic acid phenethyl ester (CAPE)—inhibit breast cancer cell proliferation in an inflammatory microenvironment by inhibiting the Toll-like receptor 4 (TLR4) signal pathway and inducing apoptosis and autophagy." (PMID 33628847, 2021). "Moreover, subsequent research showed a higher protein level of Myd88 and TLR4 in breast carcinoma than paracarcinoma tissue, as well as a correlation between their expression and axillary lymph node metastasis that providing the metastatic potential role of TLR4/Myd88 signaling in breast cancer." (PMID 33669782, 2021). "Moreover, TLR-4 expression in breast cancer correlates with poor survival rates and invasiveness." (PMID 32414156, 2020). "In the present study, we found that AT-I could inhibit the mammary tumorigenesis in rats, and the underlying mechanisms were further elucidated by detecting the effects of AT-I on TLR4/NF-κB pathway, and its downstream proinflammatory factors in breast cancer rats." (PMID 33363472, 2020). "The results showed that the secretion of TNF-α, IL-6 and IL-1β were all decreased after AT-I treatment, and we concluded that AT-I could suppress tumorigenesis in breast cancer via inhibiting TLR4/NF-κB pathway, and down-regulate downstream pro-inflammatory cytokines." (PMID 33363472, 2020). "Furthermore, AT-I could inhibit N-Nitroso-N-methylurea-induced rat mammary tumor progression through TLR4/NF-κB pathway." (PMID 33363472, 2020).
breast cancer (continued). "In addition, resistin facilitates breast cancer progression via TLR4/nuclear factor kappa-light-chain-enhancer of activated B cells (NF-κB)/signal transducer and activator of transcription 3 (STAT3) signaling pathway-mediated induction of mesenchymal phenotypes and stemness properties." (PMID 33313320, 2020). "In addition, the expression of TLR4 was the highest among other TLRs in human breast cancer, and TLR4 activation could subsequently activate nuclear factor-κB (NF-κB) and produce pro-inflammatory cytokines, ultimately stimulating inflammation." (PMID 33363472, 2020). "Thus, reducing expression of TLR4 could inhibit human breast cancer MDA-MB-231 cells proliferation and inflammatory cytokines secretion." (PMID 28950845, 2017). "Thus, activation of TLR4 signaling by LPS or endogenous ligands may foster the renewal and expansion of breast cancer stem cells." (PMID 27187369, 2016). "Yang and colleagues demonstrated that LPS triggered the metastatic spreading of human MDA-MB-231 breast cancer into liver of nude mice in a TLR4-dependent manner, which may also depend on a TLR4-dependent αvβ3-mediated adhesion of metastatic breast tumor cells to the endothelial lining." (PMID 26863029, 2016). "Finally, using a publicly available data site (R2: microarray analysis and visualization platform; Tumor breast EXPO-351) with gene expression profiles of 351 primary breast cancers, we found positive correlation between expression of TLR4 mRNA and IL-6 (r value 0.231, P = 1.3e-05)." (PMID 26392082, 2015). "Therefore, TLR4/MyD88 signaling molecules may be novel therapeutic targets in patients with breast cancer." (PMID 25299052, 2014). "Thus, we next analyzed the prognostic effect of TLR4-MyD88 activation in breast cancer." (PMID 25360699, 2014). "However, little research has investigated the role of TLR4 in breast cancer progression, and there were discrepancies of TLR4 among these studies, the mechanism of either antitumor or tumor-promoting activities is unknown." (PMID 25299052, 2014). "Similarly, silencing of TLR4 increased breast cancer metastasis." (PMID 25120541, 2014). "Therefore, our results support the notion that HA promotes tumor progression mediated by other receptors such as the receptor for HA-mediated motility (RHAMM), lymphatic vessel endothelial receptors (LYVE-1), and toll-like receptors 2 (TLR2) and 4 (TLR4) in canine mammary tumor." (PMID 23426189, 2013). "Therefore, we firstly selected TLR4 to explore whether it was able to either promote or suppress the growth of human breast cancer cell line MDA-MB-231." (PMID 20618976, 2010). "Consequently, considering the fact that the TLR4 expression by MICs is increased in breast cancer cases with recurrence, our results suggest that the use of TLR4 agonists may become a useful anticancer strategy." (PMID 21129170, 2010). "We hypothesized that after intramedullary injection of Walker 256 cells (a breast cancer cell line) into the tibia, CNS neuroimmune activation and subsequent cytokine expression are triggered by the stimulation of microglial membrane-bound TLR4." (PMID 20089147, 2010). "Within the TME, TLR4 recognizes HMGB1 to activate the MyD88/NF-κB pathway, enhancing breast cancer invasion and angiogenesis." (PMID 41488647, 2025). "The activation of the TLR4 and AGER pathways in MCF-7 and MDA-MB-231 breast cancer cell lines promotes β-catenin signaling pathway-activated cell migration." (PMID 40647480, 2025). "The natural compound triptolide was also shown to suppress breast cancer growth by directly reducing HMGB1 expression and secretion, thereby inhibiting downstream TLR4/NF-κB signaling and enhancing the efficacy of other HMGB1 inhibitors like EP." (PMID 41465435, 2025). "In breast cancer (BC), LPS facilitates EMT and cell metastasis, partly through the TLR4-Akt-GSK3β-β-catenin signaling pathway." (PMID 40444051, 2025).
breast cancer (continued). "The relationship among TLR4, AGER, and breast cancer has been documented in BC cell lines and tissue samples." (PMID 40647480, 2025). "In inflammation-stimulated breast cancer cells, CAPE and ethanol-extracted Chinese propolis (EECP) inhibit proliferation, induce apoptosis, activate autophagy, and downregulate the TLR4 signaling pathway." (PMID 38594256, 2024). "In breast cancer cells, glycation has been shown to lead to increased metastasis through activation of Receptor of AGE (RAGE)/Toll-like receptor 4 (TLR4) signaling, and anti-AGE drugs have been shown to reverse the effects on migratory behavior." (PMID 39337558, 2024). "A Arazyme activates TLR4-MyD88-TRIF, which reduces primary and metastatic tumor development in the 4T1 murine breast cancer model, thus extending survival." (PMID 38347830, 2024). "The intratumoral microbiota in breast cancer significantly influence TLR signaling, particularly through the LPS/TLR4 pathway cascade." (PMID 39926112, 2024). "Advanced glycation end products (AGEs) can promote breast cancer cell migration and invasion through the activation of the RAGE/TLR4/MyD88 signaling cascade." (PMID 38347830, 2024). "TLR4 expression and survival prognostic indicators (OS or DFS) of breast cancer patients have also been reported." (PMID 38463226, 2024). "So, we conclude that CAV1 in BC-derived sEVs promote neutrophil recruitment through the TLR4-NF-κB-IL-6/CCL2 axis and neutrophil N2-type polarization through the TLR4/NF-κB/NLRP3 pathway, thus promoting the lung metastasis of breast cancer." (PMID 39494337, 2024). "Another less explored mechanism suggests that DHA significantly increases the ratio of cyclic cAMP/cGMP levels and promotes Toll-like receptor 4 (TLR4) expression through PPARα, leading to breast cancer cell apoptosis." (PMID 37511450, 2023). "It has also been shown that TLR4, MyD88 and HMGB1 are highly expressed in invasive breast cancer cell lines compared to non-invasive cell lines." (PMID 37112730, 2023). "Like TLR4, the activation of the COX-2/PGE2 pathway has been shown to enhance the migration of breast cancer cells." (PMID 37371732, 2023). "Sufficient evidence currently exists demonstrating the crucial role of inflammation, characterized by the enhanced activation of Toll-like receptor 4 (TLR4) and the COX-2/PGE2 pathway, in the migration and proliferation of breast cancer cells." (PMID 37371732, 2023). "It has been shown that autophagic CAFs secreted HMGB1, activated Toll-like receptor-4 (TLR4, the receptor of HMGB1 found in luminal breast cancer cells), and acted on the number of cancer stem cells." (PMID 38234683, 2023). "According to recent in vitro studies in breast cancer cells, LPS increases the expression of S100A7, which inhibits TLR4 and promotes RAGE accumulation in breast carcinogenesis." (PMID 36613714, 2022). "Analysis of human breast cancer samples also highlighted the inverse correlation between S100A7 and TLR4 expression." (PMID 33969603, 2022). "According to the latest in vitro studies in breast cancer cells, LPS increases the expression of S100A7, which inhibits TLR4 and promotes RAGE accumulation in breast carcinogenesis." (PMID 36613714, 2022). "In a pre-clinical model of breast cancer, the ECM component tenascin-C promoted an immunosuppressive TAM phenotype through toll-like receptor-4 (TLR4) signaling." (PMID 35435599, 2022). "In summary, our results indicate that S100A7 counteracts the expression of TLR4 in response to LPS treatment, which in turn activates the RAGE‐mediated downstream signaling in breast cancer cells." (PMID 33969603, 2022). "The results of our recent studies revealed that TLR4 blockade using highly selective TLR4 inhibitor TAK‐242 suppresses ovarian and breast cancer cell invasion through the inhibition of EMT." (PMID 33336901, 2021). "The PPI results showed that its key targets for breast cancer include PPARG, TLR-4, BDNF, and PPAR-α." (PMID 33536908, 2020).